TRIO (trio Rho guanine nucleotide exchange factor)
Description:
Guanine nucleotide exchange factor (GEF) for RHOA and RAC1 GTPases. Involved in coordinating actin remodeling, which is necessary for cell migration and growth. Plays a key role in the regulation of neurite outgrowth and lamellipodia formation. In developing hippocampal neurons, limits dendrite formation, without affecting the establishment of axon polarity. Once dendrites are formed, involved in the control of synaptic function by regulating the endocytosis of AMPA-selective glutamate receptors (AMPARs) at CA1 excitatory synapses (By similarity). May act as a regulator of adipogenesis (By similarity).
Synonyms: ARHGEF23; MEBAS; MRD44; MRD63; tgat
Tractability: Small molecule: it belongs to a druggable protein family. Antibody: the Human Protein Atlas places it where antibodies can reach. PROTAC: ubiquitination databases record sites on it; its protein half-life has been measured.
Target class: Enzyme; Transferase
Gene: Protein-coding gene on chromosome 5 (14,143,342 to 14,532,128, forward strand). Ensembl gene ENSG00000038382.
Subcellular location: Cytoplasm; Cell projection
Subcellular location (Human Protein Atlas): Cytosol; Basal body; Plasma membrane; Primary cilium; Primary cilium tip; Vesicles
Pathways (Reactome):
Signal Transduction: CDC42 GTPase cycle; G alpha (12/13) signalling events; G alpha (q) signalling events; NRAGE signals death through JNK; RAC1 GTPase cycle; RAC2 GTPase cycle; RAC3 GTPase cycle; RHOA GTPase cycle; RHOG GTPase cycle; RHOJ GTPase cycle
Developmental Biology: DCC mediated attractive signaling
Gene Ontology:
Molecular function: protein binding; guanyl-nucleotide exchange factor activity; protein serine/threonine kinase activity; ATP binding; protein kinase activity; protein serine kinase activity
Biological process: neuron projection morphogenesis; postsynaptic modulation of chemical synaptic transmission; axon guidance; cell surface receptor protein tyrosine phosphatase signaling pathway; negative regulation of fat cell differentiation; regulation of small GTPase mediated signal transduction
Cellular component: cytosol; glutamatergic synapse; presynaptic active zone; cytoplasm; extrinsic component of membrane; postsynapse
Genetic constraint (gnomAD): Loss-of-function variants: 58 observed, 332.93 expected, observed/expected ratio (o/e) 0.17, 90% interval 0.14 to 0.22. The upper end of that interval is the gene's LOEUF score, 0.22, which puts it in group 1 of 6, group 1 being the genes least tolerant of losing a copy. Missense variants: 3,106 observed, 3,909.5 expected, observed/expected ratio (o/e) 0.79, 90% interval 0.77 to 0.82. Synonymous variants: 1,693 observed, 1,541.9 expected, observed/expected ratio (o/e) 1.1, 90% interval 1.05 to 1.14.
Gene-disease validity (ClinGen):
ClinGen rates the evidence that TRIO causes each of these diseases.
syndromic intellectual disability (autosomal dominant): Definitive. A intellectual disability that is part of a larger syndrome.
Homologues: Orthologues: chimpanzee TRIO (99% identical), macaque TRIO (99% identical), pig TRIO (97% identical), mouse Trio (97% identical), rat Trio (96% identical), rabbit TRIO (95% identical), guinea pig TRIO (95% identical), tropical clawed frog trio (89% identical), zebrafish trioa (81% identical), dog TRIO (59% identical), dog TRIO (8% identical). Paralogues in human: KALRN (63% identical), PLEKHG4B (10% identical), MCF2L (9% identical), ARHGEF25 (9% identical), ARHGEF40 (8% identical), PLEKHG4 (8% identical), TIAM2 (8% identical), TIAM1 (8% identical), MCF2 (7% identical), MCF2L2 (7% identical), PLEKHG1 (5% identical), SPATA13 (5% identical), and 10 more.
Diseases named in the same sentence as TRIO in open-access papers:
TRIO is named in the same sentence as 69 diseases in open-access papers, as found by Europe PMC text mining. Sharing a sentence is not in itself a finding about the gene and the disease. The quoted sentences say what the papers report.
Intellectual disability (17 papers, 2018 to 2025). "Rac1 mutations associated with intellectual disability impair synaptic plasticity, and variants in the RhoGEF TRIO can cause ASD, intellectual disability, schizophrenia, or macrocephaly, with severe phenotypes predicted by Rac1 overactivation." (PMID 37255534, 2023). "We also found SNVs in a male patient with intellectual disability in a gene (TRIO) with c.2105C > A variant in heterozygous form and classified as pathogenic." (PMID 36937954, 2023). "The reported clinical phenotypes of affected individuals with TRIO mutations include intellectual disability, behavioral difficulties such as hyperactivity or aggression, autism or autistic behavioral tendencies, skeletal hand anomalies, and microcephaly." (PMID 32109419, 2020). "Pathogenic variants in TRIO are associated with neurodevelopmental diseases, including intellectual disability (ID) and autism spectrum disorders (ASD)." (PMID 32109419, 2020). "Recently, mutations of the gene TRIO, which is involved in neurite outgrowth and synaptic transmission, have been identified in four patients with mild to borderline intellectual disability and behavioral abnormalities." (PMID 29685133, 2018). "TRIO is a Rho guanine nucleotide exchange factor (RhoGEF) that is critical to glutamatergic synaptic function and is associated with autism spectrum disorder/intellectual disability (ASD/ID)." (PMID 39669196, 2024). "Trio is important in neuronal development and synapse function and has been previously associated with cognitive ability: mutations in TRIO lead to intellectual disability in humans, and hippocampal and cortical knockout of Trio leads to impaired learning in memory in mice." (PMID 33042997, 2020). "Interestingly, the dysfunction of TRIO causes mild intellectual disability and Rho GTPases regulated by TRIO are involved in the processes of synaptic loss and β-amyloid production." (PMID 30140277, 2018). "Rare variants that impact TRIO GEF1 function are associated with autism spectrum disorder, developmental delay, and intellectual disability, but variants are also found throughout the gene." (PMID 40581118, 2025). "Rare predicted damaging variants in the TRIO gene are linked to autism spectrum disorder (ASD), bipolar disorder (BP), intellectual disability (ID), developmental delay (DD), and schizophrenia (SCZ) and have also been observed in epilepsy (Epi)." (PMID 40581118, 2025). "Genetic variants in TRIO are associated with neurodevelopmental disorders (NDDs) including schizophrenia (SCZ), autism spectrum disorder (ASD), and intellectual disability." (PMID 40488445, 2025). "Individuals with mutations in TRIO present with a range of NDD-associated clinical features, including varying degrees of intellectual disability, altered head size, skeletal and facial features, and behavioral abnormalities." (PMID 40488445, 2025). "For example, TRIO SR8 variants are linked to developmental delay and macrocephaly in humans and cause increased Rac1 (GEF1) activity in cells, whereas most mutations in the GEF1 domain are linked to mild intellectual disability, microcephaly, and reduced Rac1 activity in cells." (PMID 35963430, 2022).
microcephaly (14 papers, 2020 to 2025). A congenital or acquired developmental disorder in which the circumference of the head is smaller than normal for the person's age and sex. "A nonsense variant c.2149C > T in the TRIO gene with likely pathogenic predictions probably contributed to the phenotypic feature of microcephaly present only in one of the twin boys." (PMID 40988857, 2025). "After adjusting for body weight, both the head width and brain weight were reduced in P42 adult +/K1431M mice of both sexes relative to WT, consistent with the microcephaly seen in patients harboring TRIO GEF1-deficient alleles." (PMID 40488445, 2025). "This is in contrast to the GEFD1 hotspot, which is mostly associated with milder ID, microcephaly, and reduced TRIO activity." (PMID 32109419, 2020). "Mutations in TRIO are associated with ID with microcephaly in an autosomal dominant pattern." (PMID 35640457, 2022). "Interestingly, microcephaly and macrocephaly also have been described in individuals harboring distinct variants in TRIO, a RAC1-GEF." (PMID 35203342, 2022). "The whole exome sequencing confirmed the presence of this deletion in both boys and, at the same time, led to the identification of a pathogenic SNV variant in the TRIO gene in the boy with microcephaly and delayed psychomotor development, which may explain the different phenotype of both boys." (PMID 40988857, 2025). "Patients with missense or truncating variants in TRIO that reduce GEF1 activity have mild developmental delay and microcephaly." (PMID 40488445, 2025). "This aligns with observations in other genes, such as TRIO, where opposing Rac1 modulations result in either microcephaly (OMIM#617,061) or macrocephaly (OMIM#618,825)." (PMID 40019509, 2025). "Variants in the TRIO GEF1 domain that decrease Rac1 activity are associated with milder ID and microcephaly, whereas variants in the adjacent spectrin repeat 8 domain that increase Rac1 activity are associated with more severe ID and macrocephaly." (PMID 40488445, 2025). "TRIO (OMIM * 601893) is instead a more specific interactor of RAC3 and it is linked to autosomal dominant intellectual disability 44 with microcephaly (OMIM # 617061) or macrocephaly (OMIM # 618825)." (PMID 34943902, 2021). "We identified the candidate genes PPARGC1A, CTBP1, TRIO, TERT, and CCT5 that are associated with the neuropsychomotor delay, microcephaly, and neurological alterations found in our patient." (PMID 32625234, 2020). "TRIO mutations have been identified in patients with autism spectrum disorder, microcephaly, and intellectual disability, with or without epilepsy." (PMID 37779671, 2023).
autism (11 papers, 2017 to 2025). Persistent deficits in social interaction and communication and interaction as well as a markedly restricted repertoire of activity and interest as well as repetitive patterns of behavior. "Loss‐of‐function or gain‐of‐function mutations in TRIO are associated with the behavioral phenotype of autism." (PMID 41438617, 2025). "To our knowledge, we present here the first report on the association between common variations in TRIO and autism in the Chinese Han population." (PMID 41438617, 2025). "In this study, we conducted a family‐based association study to explore the link between the GEF TRIO and autism in the Chinese Han population." (PMID 41438617, 2025). "Our findings revealed a significant association between autism and three common variants (rs32593, rs33005, and rs27479) within TRIO in 427 Han Chinese autism trios." (PMID 41438617, 2025). "Results of association analyses between 12 SNPs in TRIO and autism in 239 trios by FBAT under an additive model." (PMID 41438617, 2025). "To investigate the role of common genetic variations in autism risk, we analyzed 12 tagging single‐nucleotide polymorphisms (SNPs) in the TRIO gene." (PMID 41438617, 2025). "To investigate the potential impact of these positively associated SNPs on TRIO expression in individuals with autism, we conducted an in silico analysis." (PMID 41438617, 2025). "By using whole-exome sequencing (WES) and transmission and de novo association (TADA) analysis of rare coding variations, a study identified TRIO as a gene strongly enriched for variants likely to affect autism risk from 3871 autism cases." (PMID 32244264, 2020). "In this study, we identified an association of rs32593, rs33005, and rs27479 in TRIO with autism." (PMID 41438617, 2025). "To test whether the three SNPs in TRIO remain positive in the association with autism in the European sample, we conducted an analysis of genome‐wide association study (GWAS) results in ASDs obtained from the Psychiatric Genomics Consortium (PGC)." (PMID 41438617, 2025). "We revealed that the single‐nucleotide polymorphisms (SNPs) rs32593, rs33005, and rs27479, as well as their haplotypes, are significantly associated with autism, indicating that the common variants in TRIO might also be involved in the susceptibility of autism." (PMID 41438617, 2025). "KALRN, TRIO, and DISC1 misexpression or mutation are implicated in attention deficit hyperactivity disorder, autism, bipolar disorder, schizophrenia, and other conditions." (PMID 35440587, 2022). "Subsequently, several whole-exome and genome sequencing studies identified several TRIO variations in subjects with autism or ID co-occurring with autism." (PMID 32244264, 2020). "In conclusion, our study hints at TRIO’s potential involvement in the pathogenesis of autism." (PMID 41438617, 2025). "For example, modulating the activity of TRIO through medication or other interventions might help alleviate symptoms in individuals with autism." (PMID 41438617, 2025). "However, recent evidence suggests that TRIO also plays critical roles in cIN migration and that targeted deletion in post-mitotic cINs suffices to induce autism-like behavior and epilepsy." (PMID 37779671, 2023). "Importantly, all molecules changed in the striatal Shank3Δ11-/- mutant PSD that matched with the SFARI autism gene database were reduced and comprised the murine homologs of proteins encoded by several major ASD candidates including NCKAP1, GRIN2B and TRIO, 3 of the 65 high-risk ASD TADA genes." (PMID 28261056, 2017). "Furthermore, in our analysis, several DE miRNA targets were found to be associated with neuropsychiatric disorders, such as schizophrenia (TTN, SYNPO), depressive disorder (PPARGC1B, TIMELESS), and autism (TAF1, TRIO)." (PMID 31652596, 2019).
autism (continued). "However, our study found that the three TRIO markers examined were not linked to autism in the PGC sample, which indicated that the genetic association between TRIO and autism might have population specificity." (PMID 41438617, 2025).
schizophrenia (10 papers, 2019 to 2025). A major psychotic disorder characterized by abnormalities in the perception or expression of reality. "A further study suggests that rare variants in the neurotrophin signaling pathway, in which p75 and TRIO are key components, are implicated in schizophrenia risk." (PMID 35887306, 2022). "Additional proteins with schizophrenia rare variant associations (via the SCHEMA consortium) altered in 22q11.2del neurons included DNM3, MAGI2 and TRIO (downregulated in patient neurons) and HIST1H1E, SRRM2 and ZMYM2 (upregulated in patient neurons)." (PMID 35760976, 2022). "That said, the series of patient-derived variants associated with schizophrenia, bipolar disorder, and epilepsy within the β3-β4 loop of GEF2 suggests its potential in regulating either inter- or intramolecular interactions crucial for TRIO signaling." (PMID 40581118, 2025).
Macrocephaly (9 papers, 2020 to 2025). Occipitofrontal (head) circumference greater than 97th centile compared to appropriate, age matched, sex-matched normal standards. "Nonetheless, our data provide strong evidence that missense TRIO mutations inducing RAC1 overactivation are associated with macrocephaly." (PMID 32109419, 2020). "This important number of independent individuals with a similar phenotype reduces the potential contribution of other variants to the phenotype and strongly suggests that hyperactivation of RAC1 by TRIO is associated with macrocephaly." (PMID 32109419, 2020).
autism spectrum disorder (5 papers, 2020 to 2025). A spectrum of developmental disorders that includes autism, and Asperger syndrome. "Additionally, we observed ectodermal EtOH-induced alterations in several genes, such as LHX2, SHANK2, TRIO, ZMYND8, ARX, NRXN3 and SEMA5A, that have also been associated with autism spectrum disorder (ASD) (SFARI Gene Database, 2024; accessed: 1, August, 2024)." (PMID 40401629, 2025).
bladder cancer (5 papers, 2007 to 2023). "Alternatively, the locus 5p15 offers an opportunity to examine the amplification of several oncogenes, one of which, TRIO, has already been implicated in bladder cancer progression." (PMID 38066541, 2023). "TRIO is involved in breast, ovarian, and prostate cancer, and its amplification is associated with urinary bladder cancer." (PMID 31041889, 2019). "TRIO, which has a putative role in cell cycle regulation, was found to be amplified and highly expressed in bladder cancer that associated with proliferation and invasive phenotype." (PMID 17311676, 2007). "In fact, TRIO has been associated with progression of bladder cancer and soft tissue sarcomas." (PMID 22412903, 2012). "A total of nine chr3p25 and chr11p11 genes were functionally connected to genes in the KEGG bladder cancer pathway (E2F1, E2F3, EGFR, RAF1, RB1) or to other cancer-related genes (AKT2, PIK3CA, RB1, TRIO)." (PMID 29140994, 2017).
breast carcinoma (5 papers, 2008 to 2024). "The statistical evidence in this study leads to the conclusion that the GEF TRIO may be particularly useful as a prognostic factor in breast cancer as its level is significantly increased in tumour tissue with Tiam-1 showing a significant increase in tumour tissue from patients with poor prognosis." (PMID 18925966, 2008). "We found that only miR-432-5p was downregulated in breast cancer tissues and TNBC tissues, which was finally selected as a potential functional target of circ-TRIO." (PMID 36075896, 2022). "This is in agreement with previous reports showing a link between ABL kinases and TRIO or RAC1 and with a recent study demonstrating a negative regulatory role of the TRIO-RAC1 axis on invadopodia activity of breast carcinoma cells." (PMID 25803821, 2015). "We also found that the GEF TRIO and the GTPase RAC1 are potential downstream elements of ABL kinase negative regulation of invadopodia in TN breast cancer cells." (PMID 25803821, 2015). "For example, circ-TRIO could combine with miR-432-5p to promote tumor progression of TNBC, circROBO1 and circEZH2 functioned as protein scaffold to facilitate liver metastasis of breast cancer." (PMID 38755678, 2024). "TRIO, a member of the HCCS24 gene set (genes above the blue line), is a guanine nucleotide exchange factor (GEF) that activates RAC1 (interaction 12) and stimulates the invasive behavior of some glioblastoma and breast cancers; inhibitors of this action of TRIO have been developed." (PMID 22570691, 2012).
colorectal cancer (5 papers, 2019 to 2023). A primary or metastatic malignant neoplasm that affects the colon or rectum. "ABL1 then phosphorylates the Rac/RhoGef protein TRIO on Y2681 causing Rho activation and colorectal cancer cell invasion." (PMID 34022881, 2021). "TRIO Rho-GEF activity was upregulated by tyrosine phosphorylation at Y2681 in colorectal cancer cells expressing active ABL." (PMID 37895912, 2023). "TRIO pY2681, one of the downstream effectors in colorectal cancer and can be a prognostic marker, helping to determine the therapeutic modality of patients with colorectal cancer." (PMID 35057823, 2022). "For instance, the knockdown of TRIO suppresses the migration and invasion of cervical cancer cells, and the activation of the NOTCH-DAB1-ABL-RHOGEF protein TRIO promotes the invasion and metastasis of colorectal cancer." (PMID 36075896, 2022). "Phosphorylation of Y2681 on TRIO is correlated with poor colorectal cancer patient prognosis and inhibition of ABL suppressed cancer cell invasion in mice." (PMID 34022881, 2021). "TRIO gene promotes Colorectal Cancer Invasion and Metastasis." (PMID 35057823, 2022). "By connecting NOTCH activation to the phosphorylation of TRIO (pY2681), which results in higher TRIO Rho-GEF function and a commensurate rise in the Rho GTP level, recent research has shown a specialized role for ABL kinases in promoting colorectal cancer cell metastasis and invasion." (PMID 37895912, 2023).